IL6 (interleukin 6)
Diseases named in the same sentence as IL6 in open-access papers (continued):
Sharing a sentence is not in itself a finding about the gene and the disease.
prostate carcinoma (continued). "Further understanding of the IL-6 pathway and the effect of its soluble receptor bound form will allow for more specific utilization of IL-6 as a marker of prostate cancer progression and metastasis." (PMID 22641253, 2012). "The cytokine interleukin-6 is most commonly known for its role in inflammation but has recently been evidenced for a role in the development of different cancers including prostate cancer." (PMID 22641253, 2012). "Previous work showed that such adipose tissue has the potential to modulate prostate cancer aggressiveness, through the increased production of adipokines, namely interleukin 6 (IL-6)." (PMID 22469146, 2012). "IL-6, a pleiotrophic inflammatory cytokine, is elevated in the serum of prostate cancer patients and related to progression and metastases in prostate cancers." (PMID 22472196, 2012). "The SNPs in LEPR Gln223Arg, SPP1-66 T>G, IGF1R+3174 G>A, IGFBP3-202 A>C, FGF2+223 C>T and IL6-597 G>A, plus age and PSA remained independently associated with risk for overall, and for high-grade prostate cancer." (PMID 22792137, 2012). "Interleukin-6 and the IL-6 receptor have been identified in human prostate carcinoma and IL-6 acts as an autocrine and paracrine growth factor in androgen-refractory prostate cancer cells including PC-3 cells." (PMID 21206493, 2011). "Immunohistochemical investigation of prostate cancer metastases and xenografts showed that IL-6 is expressed in the majority of prostate cancer bone metastases and to a lesser extent in prostate cancer soft tissue metastases." (PMID 21206493, 2011). "STAT3 is activated by stimulation of IL-6 which is an important autocrine/paracrine growth factor for prostate cancers and M-110 was shown to interfere with IL-6 induced activation of STAT3." (PMID 22193779, 2011). "The DU145 prostate cancer cell line expresses an autocrine IL-6 signaling loop and was recently reported to be sensitive to the effects of a novel small molecule JAK2 inhibitor in vitro and in vivo." (PMID 21533169, 2011). "The cancer stem cell-like ALDH+ population was greater in long term IL-6 stimulated LNCaP cells compared to LNCaP cells supporting the view that prostate cancer stem cells show a pro-inflammatory phenotype." (PMID 21779382, 2011). "This confirms that IL-6 is capable of repressing Necdin expression via STAT3 in prostate cancer cells." (PMID 22046235, 2011). "Following prolonged treatment with IL-6, prostate cancer cells can alter the responsiveness to the cytokine and acquire the ability to proliferate at a higher rate and become more tumorigenic." (PMID 20420679, 2010). "The expression of IL-6 and its receptor has been demonstrated in clinical specimens of both prostate cancer and benign prostate hyperplasia, and levels of IL-6 increase in organ-confined tumors." (PMID 20420679, 2010). "By contrast, the notion that the level of IL-6 and its receptor increase during prostate carcinogenesis “in vivo” is still unchallenged, so that IL-6 is nowadays considered a good candidate for targeted therapy in prostate cancer." (PMID 19242540, 2009). "Noticeably, the cooperation between NF-κB and AP-1 appears to be essential for the constitutive deregulated production of IL-6 observed in the androgen-independent, aggressive prostate cancer cells." (PMID 19242540, 2009). "In fact, the expression of IL-6 and its receptor is consistently demonstrated in human prostate cancer cell lines and in freshly isolated cells from human prostate carcinoma and benign prostate hyperplasia." (PMID 19242540, 2009). "In conclusion, this is the first study to show enhanced sensitivity to androgen withdrawal due to overexpression of IL-6 in AD human prostate cancer LNCaP cells." (PMID 19844233, 2009). "Since reports showing elevated levels of circulating IL-6 in men with advanced prostate cancer, a number of studies have been performed to clarify how IL-6 signalling is involved in the progression of prostate cancer." (PMID 19844233, 2009).
prostate carcinoma (continued). "Consistent results have been shown that IL-6 is a pleiotropic regulator of prostate cancer cell growth, and serum IL-6 levels has prognostic significance in patients with metastatic prostate cancer." (PMID 17288583, 2007). "Approximately 50% of patients with advanced prostate cancer have elevated levels of serum IL-6 in comparison with men with normal prostates, benign prostatic hyperplasia, prostatitis and localised disease." (PMID 17595657, 2007). "As prostate cancer progresses from hormone sensitive to hormonerefractory, the circulating concentrations of IL-6 in the serum of patients increase." (PMID 17595657, 2007). "A further study demonstrated that IL-6 is responsible for drug resistance and anti-apoptotic effects in prostatic cancer cells." (PMID 16001973, 2005). "This would suggest that, in prostate cancer at least, interleukin-6 is produced by the inflammatory cells." (PMID 15700032, 2005). "Several in vitro studies on prostate cancer cell lines suggest that prostate cancer cells themselves are secreting a major portion of IL-6, although other sources cannot be excluded." (PMID 15150588, 2004). "High IL-6 serum levels are correlated with shorter survival in patients with haematological malignancies, renal cell carcinoma and prostate cancer." (PMID 12771987, 2003). "In addition, immune and inflammation-related pathways were prominent, including IL-6 signaling (in breast and prostate cancer) and Hedgehog/IGF/HGF cooperation in stem cell regulation, suggesting acquisition of cancer stemness traits." (PMID 41399370, 2026). "A deeper understanding of IL-6 functions across CAF subtypes may unlock novel precision therapy opportunities for prostate cancer." (PMID 41660621, 2026). "Although this association appears partially mediated through effects on systemic inflammation burden rather than direct effects on prostate tissue, circulating IL-6 levels have been linked to both prostate cancer incidence and mortality." (PMID 41555998, 2025). "We demonstrate its versatility in accurately detecting low-abundance miRNA signatures from human tissues, identifying upregulated miRNAs in the plasma of prostate cancer patients, and measuring elevated interleukin-6 (IL-6) and hsa-miR-21 levels in cytokine release syndrome patients." (PMID 39975368, 2025). "In addition, it has been proposed that the YY1 complex in M2 macrophages promotes prostate cancer progression by upregulating IL-6." (PMID 40422804, 2025). "Furthermore, in patients with prostate cancer, radiotherapy has been shown to induce an inflammatory response, characterised by increased serum concentrations of IL-6, IL-8, TNF-α, and TGF-β." (PMID 40724564, 2025). "Notably, a recent study showed that 27OHC impairs prostate cancer cell signaling by disrupting lipid rafts and inhibiting the IL6–JAK–STAT3 pathway." (PMID 40699946, 2025). "Additionally, FABP4 facilitates prostate cancer aggressiveness through increased secretion of IL-6 and IL-8." (PMID 39941741, 2025). "Interleukin-6 (IL6) is an inflammation-associated cytokine known to be predictive of poor disease-specific outcomes when upregulated in the serum of patients with solid tumours such as non-small cell lung cancer, prostate cancer and CRC." (PMID 39766336, 2024). "Therefore, to mitigate the expression of IL-6/JAK/STAT-3 is considered an important target for the treatment of prostate cancer." (PMID 39574470, 2024). "Moreover, CA suppresses the proliferative markers, and MAPK proteins, and induces apoptosis through inhibiting the IL-6 mediated phosphorylation of JAK/STAT-3 expression in prostate cancer." (PMID 39574470, 2024). "Importantly, the IL‐6/STAT3 signaling pathway has been recognized for its involvement in prostate cancer progression." (PMID 38832957, 2024).
prostate carcinoma (continued). "For instance, CAFs-derived SDF1 and CXCL14 can promote monocyte recruitment and trans-differentiation toward the TAM2, in turn, TAM2 can secrete SDF-1 and IL-6 to activate CAFs, further making up a positive loop that facilitates immunosuppression and prostate cancers progression." (PMID 38644492, 2024). "Similarly, in senescent prostate cancer cells induced by Pten gene loss, the SASP, encompassing factors such as IL‐1β, IL‐6, IL‐10, CXCL1 and CSF‐1, attracts MDSCs." (PMID 39270064, 2024). "Additionally, elevated IL-6 levels have been observed in patients with untreated metastatic or castration-resistant prostate cancer, correlating negatively with tumor survival and response to chemotherapy." (PMID 39125867, 2024). "Therefore, in this study, we investigated the role of caffeic acid impedes the proliferation and migration of prostate cancer by inhibiting IL-6 mediated JAK-STAT-3 in prostate cancer cells." (PMID 39574470, 2024). "These outcomes support the hypothesis that the mechanisms that produce IL-6 signaling in benign and malignant prostatic tumors are seriously damaged during persistent inflammation." (PMID 39452544, 2024). "In addition, IL-6 inhibition was a potential therapeutic strategy for increasing radiosensitivity of prostate cancer." (PMID 36138265, 2023). "In addition to evaluating T. vaginalis seropositivity, studies have assessed the effect of IL-6, a proinflammatory cytokine produced in response to T. vaginalis infection, on prostate cancer development." (PMID 37958367, 2023). "The positive relationship between IL-6 and prostate cancer and the null finding for IL-27 might be robust as the relationship retained consistent across analyses that excluded pleiotropic SNPs." (PMID 36733309, 2023). "It was found that IL-6 could inhibit the oncogenic and cell cycle protein A-mediated phosphatidylinositol 3 kinase signaling pathway on prostate cancer cells by inhibiting the anti-apoptotic effect of the gene Mcl-1 after fine expression 26,27." (PMID 37576403, 2023). "Similar analysis on T/My MPAL overexpressed genes depicted a significant association with cell cycle, cell adhesion, and immune response including tissue factor signaling, ERK1/2 signaling, IL6 signaling similar to that seen in prostate cancer, and PTEN pathways." (PMID 37845689, 2023). "Additionally, a Western-style high-fat diet, which often leads to obesity, can induce chronic inflammation, and contribute to the development of prostate cancer by upregulating inflammatory cytokines such as IL-6." (PMID 37626597, 2023). "They first demonstrated that overexpression of AR-V7 precipitated a 2.7-fold and 1.5-fold increase in expression of NFκB in LNCaP and 22Rv1 prostate cancer cells, respectively, further confirmed by a 2-fold increase in a known downstream NFκB target, interleukin (IL)-6." (PMID 37191417, 2023). "Other inflammatory cytokines like transforming growth factor-β (TGF-β) and interleukin-6 (IL-6) have been shown to mediate the neuroendocrine differentiation of numerous types of histological cancers like lung and prostate cancer by EMT, resulting in immune escape and acquired resistance." (PMID 37386520, 2023). "The odds ratio of prostate cancer was 0.92 (95% confidence interval (CI), 0.89, 0.96; P=1.58×10-05) and 1.12 (95% CI, 1.07, 1.17; P=6.61×10-07) for one standard deviation increase in genetically predicted IL-1ra and IL-6 levels, respectively." (PMID 36733309, 2023). "Also, IL-6 was found to be highly expressed in the tumor tissues of prostate cancer patients undergoing radical prostatectomy and in the sera of patients with advanced androgen-resistant prostate cancer 10,20,11." (PMID 37576403, 2023). "Previously we demonstrated that Ad-SOCS3 could inhibit the growth of human and mouse prostate cancer cells via inhibition of interleukin-6 (IL-6)/JAK/STAT signaling." (PMID 37064130, 2023).
prostate carcinoma (continued). "However, our screening assay did not identify race-specific differences in serum TNF-α, IFN-γ, and IL-8 levels, whereas IL-6 level was significantly higher in prostate cancer men of AA race than CA." (PMID 37698493, 2023). "Moreover, IL-6 has been shown to induce the differentiation of M2 macrophages and activation of myeloid-derived suppressor cells (MDSCs) in prostate cancer models." (PMID 37397366, 2023). "The roles of IL-1 and IL-6 in the pathogenesis of prostate cancer have been proposed." (PMID 36733309, 2023). "Further meta-analysis showed that IL-1ra and IL-6 remained significant effects on prostate cancer." (PMID 36733309, 2023). "Interleukin 6 (IL-6) is an anti-inflammatory myokine that has been found to activate AR-mediated gene expression via a signal transducer and activator of transcription 3 (Stat3) activator pathway in prostate carcinoma cells." (PMID 38139289, 2023). "While we observed this effect may be driven by IL-6 blockade, previous studies in prostate cancer observed elevated numbers of IFN-γ–producing CD4+ T cells upon administration of CTLA-4–blocking Abs." (PMID 36881480, 2023). "In prostate cancer, IL‐6 can form autocrine/paracrine rings locally." (PMID 36524848, 2023). "High IL-6 levels correlate with a worse prognosis in patients with prostate cancer." (PMID 36639681, 2023). "For men with prostate cancer, IL6 (b = − 1.423, 95% CI [− 17.894, 15.048], p = 0.866) and TNFα (b = − 1.905, 95% CI [− 8.542, 4.732], p = 0.574) were not statistically significant moderators of the effect of exercise intensity on changes in muscle strength (Model 3.2)." (PMID 36658635, 2023). "Finally, we evaluated the effects of IL-6 and QL serum on sensitivity of paclitaxel-resistant prostate cancer cells to paclitaxel." (PMID 35193986, 2022). "Phase II studies of anti-IL6 antibody siltuximab, in metastatic castration resistant prostate cancer and platinum resistance ovarian cancer have shown limited, but some biological effect in the latter trial, indicating potential for blocking this pathway in cancers." (PMID 35313341, 2022). "For instance, activated STAT3 was believed to be necessary for paclitaxel-induced autophagy due to the addition of IL-6, but acted to inhibit docetaxel-regulated autophagy in castration-resistant prostate cancer cells, leaving the puzzle of how STAT3 affecting autophagy unresolved." (PMID 35690866, 2022). "Indeed, lycopene exerts significant capacity to inhibit prostate cancer progression demonstrated by reduced levels of inflammatory factors including interleukin (IL)-1, IL-6, Il-8 and tumour necrosis factor-α (TNF-α) in prostate cancer cells in vitro." (PMID 35158943, 2022). "Higher IL-6 levels result in prostate cancer progression via STAT3 phosphorylation in tumor cells." (PMID 36117852, 2022). "In prostate cancer, multiple lines of evidence support IL6 to be a driver of progression." (PMID 35911788, 2022). "In addition, IL-6 serum levels measured during radiotherapy in prostate cancer patients were positively correlated with enhancement of fatigue symptoms, but this result was not statistically significant (p = 0.089)." (PMID 36368974, 2022). "Furthermore, it has been described that interleukin-6 is down regulated in human prostatic carcinoma cells which provides further evidence for this enrichment gene analysis and role of CDK2AP1 as an oncogene." (PMID 36362115, 2022). "IL-6 stimulated androgen and androgen receptor synthesis in prostate cancer cells." (PMID 35464825, 2022). "Furthermore, it was also experimentally determined that andrographolide inhibits IL-6 expression in prostate cancer cells and limits the growth of prostate cancer." (PMID 35812188, 2022). "Serum TGF beta was overexpressed in prostate cancer patients, and it increased IL-6 expression." (PMID 35464825, 2022). "Moreover, GA imposed anti-inflammatory effects on prostate cancer through inhibition of the expression of many cytokines such as IL-6." (PMID 35681628, 2022).
prostate carcinoma (continued). "Our results confirm the relationship between circulating levels of IL-6 and fatigue intensity in prostate cancer patients undergoing curative radiotherapy and may contribute to further understanding of biological factors underlying fatigue." (PMID 36368974, 2022). "In addition, these observations suggest that prostate cancer cells are more sensitive to IL-6 than normal prostate epithelial cells." (PMID 34682865, 2021). "For several reasons, IL-6 is one of the most frequently investigated cytokines in prostate cancer." (PMID 34204596, 2021). "There is a plethora of evidence that IL-6 may be involved in prostate cancer development and progression." (PMID 33920379, 2021). "According to these findings, it could be implied that in patients with advanced-stage prostate cancer, altered levels of IL-6 may have a significant role in the Rictor signaling cascade to promote cancer cell survival through the AKT and PKCα pathways." (PMID 34682865, 2021). "Here, we investigated whether IRE1α can induce IL-6 secretion via the IRE1α/XBP-1s pathway in prostate cancer cells." (PMID 34295814, 2021). "Moreover, the depletion of RB1 from RB1-proficient prostate cancer cells promoted gain of stem cell-like properties through increased expression of interleukin-6 (IL-6) and lysyl oxidase (LOX)." (PMID 34359636, 2021). "Additionally, PL inhibited the invasiveness and metastatic potential of prostate cancer cells by modulating the expressions of interleukin (IL)-6, IL-8, and MMP-9." (PMID 36046754, 2021). "Moreover, compared to men with benign conditions, levels of circulating IL-6 have been found to be elevated in patients with prostate cancer." (PMID 34681797, 2021). "Whereas the Il6 gene is transcriptionally upregulated by Arid5a in prostate cancer cells, Arid5a increases the half-life of Il6 mRNA at the post-transcriptional level in immune cells, such as macrophages, which further suggests a cell-specific function of Arid5a." (PMID 35126382, 2021). "Diosmetin treatment may modulate prostate cancer cell activation by IL-6 and IGF-1 and induces apoptosis downstream of Rictor signaling." (PMID 34682865, 2021). "The role of the IRE1α/IL-6/AR positive feedback loop in controlling castration-resistant growth of prostate cancer cells suggests that this signaling network could be a prognostic indicator and therapeutic target of CRPC." (PMID 34295814, 2021). "Here, we investigated whether IL-6-mediated AR activation can regulate IRE1α expression in prostate cancer cells." (PMID 34295814, 2021). "In addition, androgen downregulation of miR‐760 was able to regulate interleukin (IL)‐6 and then promote prostate cancer cell growth, and there was less expression of miR‐942 in high‐grade than in low‐grade prostate cancer cases at biopsy." (PMID 33605506, 2021). "In our prostate cancer patient cohort, we showed that the protein expression of IRE1α, IL-6, and AR correlated in prostate cancer tissues, which may confirm the existence of IRE1α/IL-6/AR positive feedback loop in prostate cancer tissues." (PMID 34295814, 2021). "For example, interleukin (IL)-6 was found to induce the drug resistance of prostate cancer by activating the androgen receptor (AR), and IL-4 was found to be associated with the development of CRPC by regulating coactivators of AR such as The nuclear factor-kappaB (NF-κB)." (PMID 33673284, 2021). "Studies demonstrated IL6 derived from prostate cancer cells elicits pro-tumor FAP+CAF." (PMID 34760886, 2021). "The role of IL-6 has been frequently studied in prostate cancer progression." (PMID 34204596, 2021). "Interestingly, high estrogen-alpha (ER-α) expressing CAFs inhibited tumor progression in prostate cancer, and lowered IL-6 expression in CAFs and macrophages in co-culture, suggesting that IL-6 promotes M2 polarization and the pro-tumor effects of CAFs." (PMID 34858425, 2021).